GFAP (glial fibrillary acidic protein)
Diseases named in the same sentence as GFAP in open-access papers (continued):
Sharing a sentence is not in itself a finding about the gene and the disease.
medulloblastoma (continued). "Immunohistochemistry (IHC) for glial fibrillary acidic protein (GFAP) and synaptophysin showed that the expression pattern of both GFAP and synaptophysin in medulloblastoma in both Ptch1+/−; Gadd34+/− mice and Ptch1+/−;Gadd34−/− mice was comparable with Ptch1+/−; Gadd34+/+ mice." (PMID 27802424, 2016). "GFAP‐Cre; RBlox/lox; p53lox/lox mice developed medulloblastoma at a high penetrance, and provided direct proof of the developmental origin of medulloblastoma, and later studies showed that Myc amplification leads to a large cell anaplastic phenotype, striking parallel to human medulloblastoma." (PMID 39324445, 2024). "Finally, medulloblastoma that mimic the human WNT subgroup were initiated by activating CTNNB1 mutations in dorsal brainstem precursors; however, GFAP+ cerebellar stem cells may also be the cell of origin for some WNT group tumors." (PMID 25412507, 2014). "In agreement with the observation that CNBP protein levels are decreased in the absence of AMPKα2, we observed that the pro-tumorigenic function of AMPKα2 prevails in the context of the highly penetrant [GFAP-tTA;TRE-SMOA1] mouse model of medulloblastoma." (PMID 30360486, 2018). "We note that, apart from medulloblastoma formation, no other types of tumors can be detected in the brain or the other organs of [GFAP-tTA;TRE-SMOA1] mice." (PMID 30360486, 2018). "Although medulloblastoma cells in both primary tumour and xenografts were GFAP-negative, xenografts were infiltrated by star shaped astrocytes that were interpreted as resident mouse astrocytes stained due to species cross-reactivity by the GFAP-antibody." (PMID 28417956, 2017). "From this breeding we did not observe medulloblastoma upon transgenic over expression of Bmi1 and instead virtually all tumors observed in the GFAP-Cre;Bmi1LSL; RbLox/Lox mice were pituitary tumors." (PMID 22574128, 2012). "The GFAP+ fraction in the DENDRA2+ population of M-SmoPham tumors closely matched the Gfap+ fraction of the Yfp+ population M-Smo tumors, providing an alternative confirmation of glial marker expression by descendants of Math1-Cre-expressing cells within medulloblastomas." (PMID 31863004, 2019). "High levels of the intermediate filament protein GFAP, which marks both normal and neoplastic glial cells, are detected in all Ptch1Δ/+Pn-1Δ/+ nodules, while only low or no expression is detected in Ptch1Δ/+ medulloblastomas." (PMID 25901736, 2015). "For medulloblastoma, the most significant differences in rank order were observed in CKB, GFAP, and 26S proteasome non-ATPase regulatory subunit 14 (PSMD14)." (PMID 38350915, 2024).
retinal diseases (30 papers, 2010 to 2025). "Decreases in glutamine synthetase (GS) in Müller glial cells and increases in glial fibrillary acidic protein (GFAP) production are typical markers of retina stress, a hallmark of nearly all retinal diseases." (PMID 40919860, 2025). "Increased distribution of GFAP throughout Muller glia is a common feature of a variety of retinal diseases, and correlates with neuronal degeneration and loss, resulting in retinal thinning, observed in animal models." (PMID 29997321, 2018). "Sensitive cellular response markers associated with damage in retinal diseases are the up-regulation of cytoskeletal proteins, including glial fibrillary acidic protein (GFAP) and ß-tubulin." (PMID 26977812, 2016). "GFAP expression, is a hallmark for gliosis in retinal diseases or injuries." (PMID 30894574, 2019). "Here, GFAP levels were elevated in the vitreous body of patients with retinal disease, and additionally in the anterior chamber liquid in DR patients." (PMID 40141267, 2025). "Photoreceptor cell death is a well-established characteristic observed in mouse models of retinal diseases, such as the rd10 (Pde6b) mouse model, which shows persistent accumulation of glial fibrillary acidic protein (GFAP) in Müller glia cells." (PMID 41224078, 2025). "Here, we have shown that using antibodies on a mouse model of retinal disease and the zonationTool we can clearly identify subcellular expressions changes of a common glial pathology marker (e.g. GFAP)." (PMID 36625162, 2023). "All of these retinal diseases have been reported to display increased GFAP protein levels in Müller glial cells." (PMID 37977220, 2023). "Müller cells upregulate the expression of the intermediate filament GFAP in response to retinal diseases and injuries." (PMID 33154968, 2020). "It is assumed that retinal diseases and injuries upregulate the GFAP, as well as additional intermediate filament proteins; this is thought to occur primarily in the Müller cells." (PMID 26733810, 2015). "The increased GFAP levels in EG in this study indicate the role of Müller cells in this retinal disease, too." (PMID 26279003, 2015). "GFAP is one of the early genes up-regulated in retinal diseases and reflects an inner retinal stress response to outer retinal disease." (PMID 26368928, 2015). "Additionally, retinal gliosis, indicated by increased GFAP expression, was demonstrated in a dose-dependent manner, consistent with reactive glial activation reported in other retinal diseases." (PMID 39996770, 2025). "The activation of Müller cells can be measured by GFAP expression, a marker of gliosis, which is upregulated due to retinal stress and results in degenerative changes of the inner retina and neurodegeneration in retinal diseases such as AMD." (PMID 37935821, 2023). "Anti-retinal antibodies specific for glial fibrillary acidic protein (GFAP), expressed by astrocytes and Müller cells in the retina, were detected at elevated levels compared to age-matched control patients and those with other retinal diseases." (PMID 37443742, 2023). "Indeed, GFAP is a marker of glial activation under retinal damage and was found to be increased in retinal diseases." (PMID 36142617, 2022). "The primary aim of the study was to investigate whether the highly sensitive SiMoA-established biomarker for NFL, GFAP and CXCL13 (representing neurodegeneration and -inflammation) could be detected in the bloodstream of patients with retinal disease." (PMID 40141267, 2025). "The Müller cells of healthy retinae have very low or no GFAP expression, but show reactive gliosis with dramatically upregulated GFAP expression to practically all forms of retinal stress, i.e., to various retinal diseases and injuries (reviews:." (PMID 40127097, 2025). "Next, we assessed cell apoptosis and the expression of glial fibrillary acidic protein (GFAP), which reflects nonspecific responses to retinal diseases and injuries." (PMID 34301262, 2021).
retinal diseases (continued). "The up-regulation of GFAP within the Müller cells is a remarkably ubiquitous response in retinal pathology and the most sensitive non-specific response to retinal disease and injury." (PMID 26279003, 2015). "The most sensitive non-specific response to retinal diseases and injuries, which can be used as a universal early cellular marker for retinal injury, is the upregulation of glial fibrillary acidic protein (GFAP)." (PMID 20454698, 2010). "Differential changes in the GFAP expression in Mueller glial cells is the most sensitive nonspecific response to retinal diseases and injuries and has been used as a universal early cellular marker for retinal injury." (PMID 21031137, 2010). "Because upregulation of GFAP is the most sensitive non-specific response of Müller cells in retinal disease, vitreous GFAP levels might act as a biomarker for retinal glial activation." (PMID 26279003, 2015).
leukodystrophy (29 papers, 2014 to 2026). Leukodystrophies are a group of rare, progressive, metabolic, genetic diseases that affect the brain, spinal cord and often the peripheral nerves. "This case of a patient with an extremely rare missense GFAP heterozygous variant NM_002055.5: c.54G>T (p/Gly18Val) illustrates that isolated spastic paraparesis in an adolescent should also prompt diagnostic evaluation for rare leukodystrophies." (PMID 41303265, 2025). "AxD is a severe leukodystrophy and mainly caused by GFAP mutation." (PMID 31327963, 2019). "In astrocytes, the intermediate filament GFAP (glial fibrillary acidic protein) can play important roles in injury response and can be affected in leukodystrophy." (PMID 36003149, 2022). "As elevated GFAP+ astrocytes are also abundantly present in microglia-related leukodystrophies, and glutamate toxicity is a known cause of axon pathology, a similar astrocyte phenotype could partly underlie the white matter defects in microglia-related leukodystrophies." (PMID 34282843, 2021). "Moreover, non-disease-specific and non-invasive biomarkers of neuroaxonal and astroglial injury, such as neurofilament light chain (NfL) and glial fibrillary acidic protein (GFAP) levels, can be widely applicable across leukodystrophies." (PMID 37755460, 2024). "Reactive astrocytes are a prominent feature in many of the leukodystrophies, and whether changes in CSF and/or blood levels of GFAP suggest utility as a biomarker for these conditions is just beginning as a topic for investigation." (PMID 38558318, 2024). "Based on his abnormal brain MRI, a leukodystrophy gene panel was ordered, revealing a de novo VUS in GFAP, p.R376W." (PMID 27648269, 2016). "We chose one or more leukodystrophy patient representative of each disease category, and investigated expression of claudin-5, ZO-1, laminin, PDGFRβ, α-dystroglycan and AQP4 together with UEA I and/or GFAP." (PMID 34082828, 2021). "To determine whether astrocytes in Mcl-1-deleted mice had increased NESTIN expression, as seen in these leukodystrophies, we compared NESTIN+/GFAP+ populations in P14 Mcl-1cKO mice and controls." (PMID 34873168, 2021). "Although these mice did not have a leukodystrophy, the link between GFAP and Rosenthal fibers provided sufficient rationale to pursue GFAP as a candidate gene for the disease." (PMID 31838996, 2019).
melanoma (29 papers, 2010 to 2025). A malignant, usually aggressive tumor composed of atypical, neoplastic melanocytes. "In detail, GFAP was assessed in retinal detachment, proliferative vitreoretinopathy, branch retinal venous occlusion, and even malignant melanoma, which illustrated a compromise of the blood–retinal barrier (BRB)." (PMID 38087190, 2023). "We immune-stained the brain tissues of the tumor control mice for the population and expression of microglia/macrophage (Iba1), astrocyte (GFAP) and neuron (Neu N) cells along with melanoma cells (Mel-A)." (PMID 34439274, 2021). "Total nodules [270 nodules]: 69% [186 nodules] of the all areas studied express the three neural markers [GFAP, NFP, Syn]; 69.2% [187 nodules] of the melanomas were positive for GFAP." (PMID 21080952, 2010). "The observed changes in GFAP expression could alternatively be due to neuronal-like differentiation within melanoma tumors, which may be increased in MBM." (PMID 40457397, 2025). "The presence of GFAP on melanoma cells has been described in the literature and could be explained by the shared embryo origin of melanocytes and brain cells." (PMID 32575666, 2020). "In addition, most GFP+ melanoma cells now expressed Nestin, GFAP and Tubb3, reminiscent of human melanomas known to frequently express these neuronal markers." (PMID 31685822, 2019). "Although cultured with a melanoma-conditioned medium, glial fibrillary acidic protein+ (GFAP+) SCs could also promote mRNA levels of genes, involved in immune surveillance and chemotaxis such as IL-6, transforming growth factor (TGF)-β, and vascular endothelial growth factor (VEGF)." (PMID 40376000, 2025). "Immunohistochemical examination was performed on the patient, where the specimen tested positive for Melan-A, human melanoma black 45 (HMB45), S100, glial fibrillary acidic protein (GFAP), and epithelial membrane antigen (EMA)." (PMID 39996151, 2025). "Immunohistochemical analysis revealed positive reactions for S-100 protein, antihuman melanoma black-45 (HMB-45) antibody, vimentin (VIM), Sox-10, melan-A, vascular endothelial growth factor, and glial fibrillary acidic protein." (PMID 39495986, 2024). "Considered vascular malformations, immunohistochemistry: Red-KI-67 (-), Red-Melan A (-), Red-Melanoma (-), Red-S-100 (-), CD31 (-), SMA (+), NF (+), GFAP (+)." (PMID 38816740, 2024). "When we examined expression of the same autophagy pathways in preclinical xenograft models of melanoma, we found increased autophagy pathway expression in ICr versus SQ tumors across four different xenografts, a finding which was not driven by GFAP expression." (PMID 40457397, 2025). "In primary CNS melanoma cells, positive expression of HMB45, S-100, and Melan A is observed, while meningeal epithelial membrane antigen, cytokeratin, neuron-specific enolase, and glial fibrillary acidic protein are expressed negatively." (PMID 41536409, 2025). "The absence of S-100 and GFAP expression and the lack of epithelial markers allow exclusion of metastatic carcinoma or melanoma respectively." (PMID 25253093, 2014). "These melanoma cells lacked expression of neuronal markers Nestin, GFAP and Tubb3." (PMID 31685822, 2019). "The present case report clearly demonstrated that intermediate filaments, including cytokeratin, peripherin, α-internexin, GFAP and nestin, were not expressed in the signet-ring cell melanoma, although, peripherin and nestin are commonly expressed in malignant melanoma." (PMID 24348822, 2014). "Both cell types showed negative staining for glial fibrillary acidic protein (GFAP), neuron specific enolase (NSE), HMB45, melanoma-pan, cytokeratin (CK), epithelial membrane antigen (EMA), alpha-fetoprotein (AFP), CD30, human chorion gonadotropin (HCG), SM-action, CD68, CD163, and CD34." (PMID 22515616, 2012).
Sepsis (28 papers, 2014 to 2026). Sepsis is defined as life-threatening organ dysfunction caused by a dysregulated host response to infection. "Hippocampal astrocytes (GFAP+) and primary microglia-stressed A1 astrocytes in mice with sepsis-associated encephalopathy." (PMID 38891053, 2024). "Although not included in this preliminary investigation, due to lack of data supporting associations with other relevant forms of encephalopathy at the time of writing, GFAP has since shown potential to assist early diagnosis and prognostication for sepsis-associated encephalopathy." (PMID 35176088, 2022). "In Astrocyte 1, inflammation-associated genes (GFAP, FOS, C3, CD74) were significantly upregulated, while BBB-related genes (GRIA2, NRGN, TXNIP) were downregulated in sepsis." (PMID 41030458, 2025). "If biomarkers such as S100B or GFAP are elevated, clinicians can use these markers not only as indicators of severe sepsis but also as potential flags for brain involvement." (PMID 40529149, 2025). "In the sepsis group, we observed increased GFAP positive cells at 24 h (p < 0.05) and 10 days (Dp < 0.05) in the PFC." (PMID 35606817, 2022). "Several studies have demonstrated that S100β, GFAP and NSE are serum markers of sepsis-associated brain diseases." (PMID 34705665, 2021). "An elevatedlevel of these proteins is associated with cytokine activation in sepsis.S100B, NSE, and GFAP have been used to diagnose sepsis-induced brain injury." (PMID 32779431, 2020). "Sepsis also led to higher levels of the astrocytic marker GFAP, indicating dysfunction differentiation of neurons in the hippocampal dentate gyrus." (PMID 33100215, 2020). "Astrocytes responded to sepsis with an increase in GFAP immunoreactivity in the hippocampus and primary white matter tracts." (PMID 31827139, 2019). "Using markers of microglias and astrocytes (Iba1 and GFAP), we found that glias were activated in the cortex and hippocampus during sepsis." (PMID 30186119, 2018). "In adults with sepsis and septic shock, both serum S-100β and GFAP were elevated compared to controls." (PMID 27089280, 2016). "Likewise, P2X7 absence decreased ionized calcium-binding protein 1 (Iba−1) and glial fibrillary acidic protein (GFAP) upregulation in the cerebral cortex of sepsis-surviving animals." (PMID 37153798, 2023). "In a case series, sepsis postmortem brain tissues showed GFAP expression in all of them." (PMID 35606817, 2022). "In a murine sepsis model to study the role of complement in brain pathology, LPS injection resulted in an enhanced cerebral expression of glial fibrillary acidic protein (GFAP), toll-like receptor (TLR) 4, pro-inflammatory molecules, Akt-mediated apoptotic events, and increased gliosis." (PMID 34191093, 2021). "Sepsis led to decrease in all neuronal markers in the hippocampus, except GFAP." (PMID 33100215, 2020). "A clinical study demonstrated the activation of astrocytes glial fibrillary acidic protein (GFAP) and macrophages (CD68/CD45) and the elevation of chemokines (CXCL8/10/12, CCL13/22) in the encephalon of patients diagnosed with sepsis." (PMID 37569277, 2023). "The changes in IBA-1 and GFAP in the PFC and hippocampus following sepsis were further confirmed by IF analysis." (PMID 35606817, 2022). "At 10 days after sepsis, the data shows significant increases in the IBA-1 (PFC and hippocampus, p < 0.05), GFAP (PFC, p < 0.05 and hippocampus, p ≥ 0.05), and TSPO (PFC and hippocampus, p < 0.001)." (PMID 35606817, 2022). "According to our findings, CD40 is localized on the membrane of EGCs and overexpressed during sepsis both in CLP model and LPS-induced cell model, following the increased expression of GFAP." (PMID 36303116, 2022). "Many biomarkers have been investigated in adults and children to detect sepsis-related neurological injuries, including S-100 β, neuron-specific enolase (NSE), and the astrocyte protein, glial fibrillary acidic protein (GFAP)." (PMID 27089280, 2016).
Sepsis (continued). "In spite of the changes in astrocyte morphology and TNAP activity in cerebral microvessels, SBI-425 treatment had no further effect on changes in GFAP immunoreactivity induced by sepsis." (PMID 31827139, 2019). "In experimental sepsis, the time from sepsis onset correlated with tissue neurofilament levels (R = 0.53, p = 0.045) but not glial fibrillary acidic protein." (PMID 29058589, 2017). "Examination of astrocyte morphology using GFAP immunostaining revealed no gross differences between sepsis survivors and sham controls (data not shown)." (PMID 29326685, 2017). "In septic rat brain tissue, there was a mild correlation between NfHSMI35 levels and time from sepsis induction (R = 0.53, p = 0.045) that was not seen for either GFAP (R = −0.39, p = 0.154) or total protein (R = −0.05, p = 0.854)." (PMID 29058589, 2017). "We found that Iba1 and GFAP were upregulated in WT septic mice, whereas P2X7−/− septic mice prevented this event in the cerebral cortex, indicating that the absence of the P2X7 receptor may be involved in the reversal GFAP and Iba-1 upregulation during sepsis." (PMID 37153798, 2023). "Similarly, GFAP positive cells increased at 24 h after sepsis in the hippocampus (p < 0.05) but not after 10 days (Hp ≥ 0.05)." (PMID 35606817, 2022). "There was an increase in GFAP protein levels in the cerebral cortex but not in the hippocampus of both WT and P2X7−/− sepsis-surviving animals." (PMID 37153798, 2023). "Children with sepsis had higher levels of serum NSE, S100 β and GFAP than that of controls, and serum levels of both NSE and S100 β were highest in children who did not survive sepsis." (PMID 25722876, 2014).